ORAI3 (ORAI calcium release-activated calcium modulator 3)
Description:
Pore-forming subunit of two major inward rectifying Ca(2+) channels at the plasma membrane: Ca(2+) release-activated Ca(2+) (CRAC) channels and arachidonate-regulated Ca(2+)-selective (ARC) channels. Assembles with ORAI1 and ORAI2 to form hexameric CRAC channels that mediate Ca(2+) influx upon depletion of endoplasmic reticulum Ca(2+) store and channel activation by Ca(2+) sensor STIM1, a process known as store-operated Ca(2+) entry (SOCE). Various pore subunit combinations may account for distinct CRAC channel spatiotemporal and cell-type specific dynamics. ORAI1 mainly contributes to the generation of Ca(2+) plateaus involved in sustained Ca(2+) entry and is dispensable for cytosolic Ca(2+) oscillations, whereas ORAI2 and ORAI3 generate oscillatory patterns. CRAC channels assemble in Ca(2+) signaling microdomains where Ca(2+) influx is coupled to calmodulin and calcineurin signaling and activation of NFAT transcription factors recruited to ORAI1 via AKAP5. CRAC channels are the main pathway for Ca(2+) influx in T cells and promote the immune response to pathogens by activating NFAT-dependent cytokine and chemokine transcription. Assembles with ORAI1 to form channels that mediate store-independent Ca(2+) influx in response to inflammatory metabolites arachidonate or its derivative leukotriene C4, termed ARC and LRC channels respectively.
Synonyms: TMEM142C; MGC13024
Tractability: Antibody: UniProt places it where antibodies can reach, with high confidence; its Gene Ontology location is reachable by antibodies, with high confidence; UniProt predicts a signal peptide or a membrane-spanning region. PROTAC: ubiquitination databases record sites on it; a small molecule that binds it is known.
Gene: Protein-coding gene on chromosome 16 (30,949,068 to 30,956,461, forward strand). Ensembl gene ENSG00000175938.
Subcellular location: Cell membrane
Subcellular location (Human Protein Atlas): Cytosol; Nucleoplasm
Gene Ontology:
Molecular function: protein binding; store-operated calcium channel activity
Biological process: store-operated calcium entry; calcium ion transmembrane transport
Cellular component: plasma membrane; membrane
Genetic constraint (gnomAD): Loss-of-function variants: 15 observed, 14.61 expected, observed/expected ratio (o/e) 1.03, 90% interval 0.69 to 1.57. The upper end of that interval is the gene's LOEUF score, 1.57, which puts it in group 6 of 6, group 1 being the genes least tolerant of losing a copy. Missense variants: 405 observed, 392.17 expected, observed/expected ratio (o/e) 1.03, 90% interval 0.95 to 1.12. Synonymous variants: 178 observed, 165.3 expected, observed/expected ratio (o/e) 1.08, 90% interval 0.95 to 1.22.
Homologues: Orthologues: chimpanzee ORAI3 (99% identical), macaque ORAI3 (97% identical), pig ORAI3 (93% identical), dog ORAI3 (92% identical), guinea pig ORAI3 (91% identical), rabbit ORAI3 (91% identical), rat Orai3 (90% identical), mouse Orai3 (89% identical), Drosophila melanogaster Orai (42% identical), Caenorhabditis elegans orai-1 (31% identical). Paralogues in human: ORAI1 (54% identical), ORAI2 (53% identical).
Diseases named in the same sentence as ORAI3 in open-access papers:
ORAI3 is named in the same sentence as 61 diseases in open-access papers, as found by Europe PMC text mining. Sharing a sentence is not in itself a finding about the gene and the disease. The quoted sentences say what the papers report.
breast carcinoma (67 papers, 2011 to 2025). "For instance, after second passage, we identified differences in methylation levels in the island area of the ORAI3 gene, the overexpression of which has been linked to chemotherapy resistance in breast cancer." (PMID 38069103, 2023). "In another study, the upregulation of Orai3 together with TRPC1 in breast cancer has been linked to HIF-1α, as its silencing reduced the expression of both channels." (PMID 36612099, 2022). "Breast cancers with high ORAI3/low ORAI1 were associated with poorer RFS in basal, ERα-negative and TNBCs, and low ORAI3/high ORAI1 associated with good outcome." (PMID 30754719, 2019). "Remarkably, in breast cancer, estrogen receptor-positive breast cancer cells are associated with elevated levels of Orai3, which is an estrogen receptor α-regulated Ca2+ channel." (PMID 29951353, 2017). "Overexpressed ORAI3 was shown to encode SOCE in a subset of breast cancer cells that partially substituted for functional ORAI1 channels." (PMID 27013185, 2016). "Moreover, the Orai3 channel was implicated in resistance to chemotherapeutic drugs (including CDDP) in breast cancer cells." (PMID 34065942, 2021). "Moreover, Orai3 expression was reported to be upregulated in the mesenchymal subtype of breast cancer cells suggesting that higher Orai3 levels are associated with the mesenchymal nature of cancerous cells." (PMID 34885048, 2021). "However, SOCE in less aggressive, estrogen receptor positive luminal subtype of breast cancer cells occurs mainly through ORAI3, and upon loss of estrogen receptor alpha, metastatic cells appear to switch to SOCE through the ORAI1 channel." (PMID 30034631, 2018). "The potential mechanisms underlying Orai3 up-regulation in ER+ breast cancer cells remain unclear." (PMID 34768857, 2021). "Finally, the importance of ORAI3 in conferring chemoresistance has been underscored by a recent study that linked ORAI3 overexpression and chemoresistance in human breast cancer data sets, and further demonstrated that ORAI3 overexpression conferred chemoresistance properties to cells." (PMID 30034631, 2018). "Similar to PCa, the expression of ORAI3 channels is often increased in breast cancer (BC), involving cancer cell proliferation, cell cycle development, and survival." (PMID 38672434, 2024). "For example, one study has shown that Orai3 is the SOCE-mediated protein that plays a major role in estrogen receptor-positive breast cancer cells." (PMID 37047790, 2023). "Specifically, in invasive breast cancer cell lines, the reduction of Orai3 through knockdown led to a decline in cell migration, while the augmentation of Orai3 expression resulted in an enhancement of cellular motility." (PMID 37759448, 2023). "Induced overexpression of Orai3 in T47D breast cancer cells led to resistance to cisplatin, 5-fluouracil and paclitaxel." (PMID 35207698, 2022). "Again, Orai3 overexpression, protects T47D cells against cell death inducers like cisplatin, fluorouracil, paclitaxel, staurosporin and thapsigargin, suggesting a role for Orai3 in breast cancer resistance to chemotherapeutics." (PMID 35163823, 2022).
breast carcinoma (continued). "Regarding the role of Orai3 in the CSC phenotype acquisition in cancer cells, it has been demonstrated that Orai3 overexpression is correlated with tumoral aggressiveness and chemoresistance acquisition in breast cancer cells." (PMID 35456011, 2022). "For example, in breast cancer cells and tissue, Orai3 expression was significantly higher and that knockdown of Orai3 led to cell cycle arrest and apoptosis." (PMID 35821821, 2022). "In various breast cancer cells, hypoxia increased Orai3 expression, though the expression levels of other Orai isoforms were unaffected." (PMID 36612099, 2022). "Whilst Orai1 was widely studied in chemoresistance, recent work had established a strong link between Orai3 and resistance in breast cancer." (PMID 35207698, 2022). "Previously, the same group demonstrated that Orai3 expression is also positively correlated with the oncogene c-myc expression in the ER-positive (luminal-like) breast cancer cell line MCF7." (PMID 35456011, 2022). "Orai3 expression in MCF7 breast cancer cells has been reported to be dependent on ERα since ERα knockdown significantly reduced Orai3 expression in these cells." (PMID 34768857, 2021). "The key findings of our study are: (i) Orai3 regulates basal-like breast cancer cell migration via a modulation of adhesive capacities." (PMID 34943998, 2021). "Together, our results reveal new mechanisms by which Orai3 regulates breast cancer cell aggressiveness." (PMID 34943998, 2021). "ORAI3 calcium channel, overexpressed in most ER+ breast tumors, regulates tumor cell growth, invasion, and in vivo breast cancer progression by controlling NFAT activity and ERK1/2 and FAK phosphorylation." (PMID 33568645, 2021). "Similar to breast cancer cells, in lung cancer cells Orai3 expression has also been demonstrated to be regulated by ERα." (PMID 34360783, 2021). "Overall, these studies highlight the significant role of Orai3 to potentially function as a therapeutic target in breast cancers." (PMID 34360783, 2021). "In order to understand the mechanisms by which Orai3 regulates migration we studied the impact of the downregulation of Orai3 by siRNA on cell migration in two aggressive breast cancer cell lines namely MDA-MB-231 (MDA-231) and MDA-MB-231 BrM2 (MDA-BrM2)." (PMID 34943998, 2021). "In breast cancer, elevated ORAI1 and lower ORAI3 levels are features of basal breast cancers, and in prostate cancer cells, reduced SOCE confers resistance to some apoptotic pathways." (PMID 34573310, 2021). "Orai3, on the other hand, regulates the progression of certain specific subtypes of breast cancers by forming a functional SOCE channel." (PMID 34885048, 2021). "In breast cancer, bioinformatics analyses revealed that Orai3 mRNA expression was higher in tumors from patients with poor response to therapy than those from patients whose response was good or complete." (PMID 34065942, 2021). "In the present study, we investigated the role of Orai3 in migration and adhesion of basal-type ER− breast cancer cells." (PMID 34943998, 2021). "In breast cancer cells, Orai1 and TRPC6 are upregulated in the estrogen receptor positive (ER+) and triple negative subtypes, and Orai3 is overexpressed exclusively in the ER+ breast cancer subtype." (PMID 34439314, 2021). "Here, we focused on studying the role of the Orai3 channel in the cell migration mechanisms of the most aggressive type of breast cancer." (PMID 34943998, 2021).
breast carcinoma (continued). "From the functional point of view, SOCE in MCF7 is mediated by STIM1, STIM2, and Orai3, in contrast to other breast cancer subtypes, such as TNBC cells, where SOCE is entirely dependent on STIM1 and Orai1." (PMID 34439314, 2021). "The ORAI3 expression is also elevated in breast cancer cells, where enhanced ORAI3-dependent SOCE result in apoptosis resistance, proliferation, and invasion in an estrogen receptor-dependent way." (PMID 32733237, 2020). "Conversely, luminal breast cancer cell lines generally have higher ORAI3 expression and exhibit greater ORAI3‐mediated Ca2+ entry compared to basal breast cancer cell lines." (PMID 31647602, 2020). "Overall, Orai1-mediated SOCE plays a crucial role in breast cancer cell metastasis, while Orai3 is involved in proliferation and cell survival." (PMID 33333945, 2020). "Overexpression of Orai3 protein in ER+ breast cancer cells revealed consistent chemoresistance against cisplatin, 5-FU and paclitaxel treatments." (PMID 30884858, 2019). "Here, we sought to define ORAI1 and ORAI3 expression in breast cancer cell lines of different molecular subtypes and assess the potential role and regulation of ORAI3 in basal breast cancer cells." (PMID 30754719, 2019). "To define levels of ORAI1 and ORAI3 in breast cancer molecular subtypes, we assessed RNA sequencing (RNA-Seq) data from the TCGA breast cancer database (845 tumors)." (PMID 30754719, 2019). "Our study demonstrates that elevated ORAI1 is a feature of basal-like breast cancers, while elevated ORAI3 is a feature of luminal breast cancers." (PMID 30754719, 2019). "It has been demonstrated that SOCE in estrogen receptor (ER)-positive breast cancer cells is mediated by Orai3 and STIM2/STIM1, whereas SOCE in ER-negative breast cancer cells mostly depends on the canonical Orai1/STIM1 pathway." (PMID 31252656, 2019). "Orai3 transcripts are differentially expressed in the different subtypes of breast cancer and regulated by estrogen receptor alpha (ERα)." (PMID 30935064, 2019). "Future studies should also assess the potential opportunities presented by ORAI3 silencing/inhibition to alter inflammatory and immune responses in breast cancer." (PMID 30754719, 2019). "ORAI3 levels were significantly lower in basal breast cancers overall; however, ORAI3 levels were high in some basal breast cancers, and we observed significantly higher ORAI3 levels in TNBCs of the MES and LAR molecular subtypes." (PMID 30754719, 2019). "In ER+ breast cancer cells, Orai3-dependent survival was found to be transduced—at least in part—via the ERK and c-myc pathway." (PMID 30884858, 2019). "Assessment of a publicly available microarray dataset, showed that increases in ORAI3 were also evident in ERα-positive MCF-7 breast cancer cells, HT29 colon cancer cells and Du145 prostate cancer cells proportionate to increased exposure to hypoxia." (PMID 30754719, 2019). "ORAI3 levels increased in two other basal-like breast cancer cell lines (HCC1569 and MDA-MB-231) and the EMT breast cancer cell line model PMC42LA, under hypoxic conditions." (PMID 30754719, 2019). "In the case of MDA-MB-468 breast cancer cells, hypoxia-induced induction of ORAI3 is mediated by HIF1α, placing ORAI3 alongside TRPC1 as a HIF1α-inducible ion channel in this model." (PMID 30754719, 2019). "This study defines ORAI3 as a potential fine-tuner for processes relevant to the progression of basal breast cancers." (PMID 30754719, 2019).
breast carcinoma (continued). "Overexpression of Orai3 reduced the sensitivity of cell death response to chemotherapeutic agents, including cisplatin, 5-fluorouracil, and paclitaxel in ER-positive T47D breast cancer cells." (PMID 31252656, 2019). "In contrast to ORAI1, the enrichment of ORAI3 in clinical breast cancer samples is largely unexplored." (PMID 30754719, 2019). "The importance of Orai3 in conferring chemotherapy resistance has been highlighted in a recent study employing large human breast cancer data sets." (PMID 31252656, 2019). "These cell line-based studies predict that ORAI3 levels should be low in breast cancers of the basal molecular subtype, due to their extensive overlap with breast cancers that are ERα-negative." (PMID 30754719, 2019). "Hypoxia induced ORAI3 levels in basal breast cancer cell lines through a pathway involving hypoxia-inducible factor-1 alpha (HIF1α)." (PMID 30754719, 2019). "Binding motifs for the hypoxia response regulators and transcription factors HIF1α and HIF1β were present in the ORAI3 promotor in MCF7 cells indicating an ability for HIF1 factors to bind in breast cancer cells." (PMID 30754719, 2019). "In this study, we sought to define ORAI3 mRNA expression in breast cancers of different molecular subtypes and compare expression profiles in relation to ORAI1 expression." (PMID 30754719, 2019). "Orai3 was primarily described as involved in proliferation, cell cycle progression, and Estrogen Receptor positive (ER+) breast cancer cells survival." (PMID 30884858, 2019). "Concerning other Orai isoforms, different studies have demonstrated that the expression of Orai3 is elevated at the transcript and/or protein level in ER+ breast cancer cell lines and human clinical samples." (PMID 30558192, 2018). "Through a combination of bioinformatic analysis and in vitro experiments, Hasna and coworkers have found a correlation between Orai3 overexpression and chemoresistance in several breast cancer data sets." (PMID 30558192, 2018). "Our results confirm that Orai1 is overexpressed in the breast cancer cell lines and that Orai3 expression is significantly enhanced in MCF7 (p < 0.05; n = 6), as previously reported." (PMID 30223530, 2018). "Consistent with this, the expression of a variety of Ca2+ channels is up-regulated in breast cancer cell lines and cancerous tissue, including Orai1, Orai3 and different TRP channels, such as TRPC6, TRPV6 and TRPM8, among others." (PMID 30558192, 2018). "It was previously reported that the Orai3 channel selectively mediates SOCE signaling in estrogen receptor α-positive breast cancer cells." (PMID 26919241, 2016). "Studies in breast cancer cells have shown that expression and activity of c-Myc is regulated by ORAI3, which is upregulated in PDACs (TCGA data)." (PMID 26440150, 2015). "Thirdly, the native SOCE pathway was found to be mediated by Orai3 in estrogen receptor-positive breast cancer cells whereas the canonical STIM1/Orai1 pathway was shown to be used by estrogen receptor-negative breast cancer cells." (PMID 24797725, 2014). "We have previously shown in breast cancer cells that Orai3 silencing suppressed cell proliferation, arrested cell cycle in the G0/G1 phase, and this phenomenon is associated with a reduction in CDKs 4/2 and cyclins D1 and E expression." (PMID 24058448, 2013). "It has been demonstrated recently that Orai3 is a part of a native store-operated Ca2+ entry pathway in the estrogen receptor (ER) positive breast cancer cells." (PMID 24058448, 2013). "In breast cancer tissue, Orai3 is up-regulated when compared to healthy tissue and its signaling includes cell cycle progression, apoptosis resistance, the mitogen-activated protein (MAP) kinase pathway and tumor formation." (PMID 24240085, 2013).